GNAS (GNAS complex locus)
Diseases named in the same sentence as GNAS in open-access papers (continued):
Sharing a sentence is not in itself a finding about the gene and the disease.
type 2 diabetes (3 papers, 2019 to 2024). "The target genes that were significantly enriched for the development of type II diabetes mellitus in both modules are GNAS, PRKACB, PRKCE, MAP4K4, PEA15, and BDNF." (PMID 32993798, 2020). "Our approach delineated that hsa-miR-933 might control the hyperglycemic condition and hyperinsulinism by regulating ATF2 target genes MAP4K4, PRKCE, PEA15, BDNF, PRKACB, and GNAS which can otherwise lead to the development of type II diabetes mellitus." (PMID 32993798, 2020). "From this information, it can be considered for the analysis if hsa-miR-933 can regulate the overexpressed PEA15, downregulated BDNF, or other ATF2 target genes (PRKACB, GNAS, PRKCE, and MAP4K4) to control type II diabetes mellitus." (PMID 32993798, 2020).
alcoholism (2 papers, 2007 to 2015). "The two prioritized candidate gene lists (87 genes for FAS and 65 for alcoholism) had only two high priority candidate genes in common – GNAS complex locus (GNAS) and high mobility group protein B1 (HMGB1)." (PMID 17961254, 2007). "Of these 6 genes, LPAR1, PSD3, and GNAS are associated with brain-related phenotypes (alcoholism, memory, and brain waves), and LPAR1, PSD3, GNAS, and SRPK2 with eQTLs annotated in GTex or PheGenI in any human tissue (brain regions are not well represented in GTEx)." (PMID 26597164, 2015).
B-cell lymphoma (2 papers, 2021 to 2024). "We identified 666 mutations from 262 genes in baseline cfDNAs from 79 B-cell lymphoma patients, and found some genes were preferentially mutated in our cohort such as GNAQ, GNAS, H3F3A, DNMT3A, HLA-A, and HLA-B." (PMID 34926267, 2021). "In addition to retrotransposon alterations, our integrated analysis of ATAC-seq and RNA-seq further reveals a potential link between GNAS KO plus HDAC3 inhibition and the ETS family transcription factors PU.1 and SpiB for transcriptional regulation of IFN signal activation in B-cell lymphoma." (PMID 39117798, 2024).
bladder cancer (2 papers, 2014 to 2023). "GNAS and GNAI1 were not differentially expressed in recurrent bladder cancer samples, although these were associated with the 5hmC DMR in the promoter regions." (PMID 37138354, 2023).
cholangiocarcinoma (2 papers, 2013 to 2017). A carcinoma that arises from the intrahepatic biliary tree (intrahepatic cholangiocarcinoma) or from the junction, or adjacent to the junction, of the right and left hepatic ducts (hilar cholangiocarcinoma). "There have been only a few studies on GNAS mutation in cholangiocarcinomas and IPNBs, to our knowledge." (PMID 24312577, 2013). "Of note, neither GNAS nor RNF43 mutations, which arose in cholangiocarcinoma as reported, were found in our samples." (PMID 28008139, 2017).
cholestasis (2 papers, 2019 to 2023). Impairment of the bile flow caused by obstruction within the liver, or outside the liver in the bile duct system. "GNAS mutations had a high positive rate (83.3%–100%) in liver tissue with cholestasis." (PMID 37886236, 2023). "Altogether these changes can be thought of as an effect of the GNAS mutation on the liver cells and may appear, as previously suggested, consistent with an imperfect morphogenesis of the intrahepatic bile duct system leading to cholestasis." (PMID 31485549, 2019).
chronic lymphocytic leukemia (2 papers, 2014 to 2020). "Besides, the T393C polymorphism of GNAS is associated with increased Gsɑ mRNA expression in solid tumors and in chronic lymphocytic leukemia (CLL)." (PMID 33299887, 2020).
colon adenoma (2 papers, 2017 to 2019). An adenoma that arises from the colon.
craniosynostosis (2 papers, 2016 to 2018). Craniosynostosis is defined as the premature fusion of one or more cranial sutures leading to secondary distortion of skull shape resulting in skull deformities with a variable presentation. "Recently, a research group reported that a 6-month-old patient with PHPIA caused by GNAS mutation had round face and craniosynostosis, which is characterized by synostosis of the coronal, frontal, and sagittal sutures." (PMID 26859889, 2016). "Interestingly, Wnt1-cre;Gsαf/f mutants show round face, shortened snout, hypertelorism and craniosynostosis, these phenotypes are highly similar to the clinical phenotypes observed in GNAS mutations diseases." (PMID 26859889, 2016).
differentiated thyroid carcinoma (2 papers, 2023 to 2025). Differentiated thyroid carcinoma (DTC), also known as papillary or follicular thyroid carcinoma, is a slow-growing malignancy usually presenting in adults as an asymptomatic thyroid mass. "According to Yoshimo and al, GNAS variants at codons 201 or 227 may play a role in the pathogenesis of a small population of papillary thyroid carcinomas." (PMID 40078582, 2025).
duodenal adenocarcinoma (2 papers, 2021 to 2025). A carcinoma that arises from glandular epithelial cells of the duodenum. "Additionally, previous studies have reported that the frequency of GNAS mutations is at most 10% in duodenal adenocarcinomas, suggesting that most duodenal adenocarcinomas are not derived from gastric-type duodenal adenomas." (PMID 40463821, 2025).
gastric adenoma (2 papers, 2020 to 2021). A neoplastic polyp that arises from the stomach. "Interestingly, sporadic fundic gland polyps also show activating mutations in β-catenin; however, GNAS mutations are either absent or infrequent in conventional gastric adenomas and adenocarcinomas." (PMID 33097069, 2020).
gestational diabetes (2 papers, 2014 to 2018). Carbohydrate intolerance first diagnosed during pregnancy. "Increased methylation at differentially methylated regions of GNAS has been described in infants born in conditions of gestational diabetes." (PMID 29930742, 2018).
hyperparathyroidism (2 papers, 2024). Hyperfunction of the parathyroid glands resulting in the overproduction of parathyroid hormone. "The proband also demonstrated hyperparathyroidism and severe bone deformities explained by a blended phenotype due to an additional somatic GNAS mutation." (PMID 38528055, 2024). "Hyperparathyroidism in the proband can be explained neither by GNAS nor TRPV5 mutations alone." (PMID 38528055, 2024).
Hypokalemia (2 papers, 2022 to 2025). An abnormally decreased potassium concentration in the blood. "Further research is warranted to elucidate the underlying mechanisms of hypokalemia in PHP1B—particularly those involving methylation defects at the GNAS locus—and to inform the development of targeted, mechanism-based treatment strategies." (PMID 40893942, 2025). "Notably, the GNAS-hypokalemia association currently derives from physiological inference rather than direct molecular evidence–a gap necessitating targeted epigenotype-phenotype studies." (PMID 40893942, 2025). "No other mutations in GNAS or hypokalemia related genes and no deletions of STX16 exons were detected." (PMID 35410271, 2022).
Hyponatremia (2 papers, 2016 to 2022). An abnormally decreased sodium concentration in the blood. "Only after the finding of the missense variant p.Ile56Phe in exon 2 of GNAS gene we related these data to the hyponatremia." (PMID 35197096, 2022). "We do not have a clear explanation for the prior history of hyponatremia; however, it is intriguing to hypothesize that there could be tissue-specific effects of this mutation because of the imprinting of the GNAS locus." (PMID 27579188, 2016).
intrauterine growth restriction (2 papers, 2013 to 2017). "Intrauterine growth retardation (IUGR) has been frequently observed in patients with inactivating GNAS coding mutations." (PMID 29280743, 2017).
invasive breast carcinoma (2 papers, 2019 to 2023). A carcinoma that infiltrates the breast parenchyma. "Additionally, COMMD4_AS1, GNAS, POLDIP3, FASTK, and RHOC AS were significantly associated with METTL3 deletion whereas AS of EXOC7 correlated with both deletion and gain of METTL3 in invasive breast carcinoma." (PMID 36725888, 2023).
Leydig cell tumor (2 papers, 2012 to 2023). A sex cord-stromal tumor occurring in the testis and rarely in the ovary. "A case report showed that a GNAS-activating mutation caused a Leydig cell tumor and hypertestosteronemia." (PMID 38012716, 2023).
liposarcoma (2 papers, 2015 to 2024). A usually painless malignant tumor that arises from adipose tissue. "However, these profiles did not segregate by histology (lung adenocarcinoma-appendiceal cancer (KRAS G12D and GNAS R201C), and lung adenocarcinoma-liposarcoma (CDK4 and MDM2 amplification pairs))." (PMID 26418953, 2015).
liver disease (2 papers, 2021 to 2023). "Other relatively strong positive associations are found between liver disease etiology and genes IDH1 and ARID1A (phi = 0.82 and phi = 0.77 for HCV and HIV infection, respectively), and a moderate association was also observed between HBV infection and GNAS (phi = 0.68)." (PMID 34885159, 2021).
lung adenocarcinoma (2 papers, 2015 to 2018). A carcinoma that arises from the lung and is characterized by the presence of malignant glandular epithelial cells. "Our primary screen generated a functionally annotated list of 28 genes that led to robust metastatic dissemination and merit further interrogation, including some that have been previously identified to be mutated in lung adenocarcinoma (GNAS, MAPK6, ACVR1B, FBXW7, NTRK3)." (PMID 30013058, 2018).
lymphoma (2 papers, 2022 to 2024). A malignant (clonal) proliferation of B- lymphocytes or T- lymphocytes which involves the lymph nodes, bone marrow and/or extranodal sites. "In this study, we identify that knockout (KO) of GNAS, a gene encoding the G-protein α subunit (Gαs), sensitizes resistant lymphoma cells to HDAC3 inhibition using unbiased genome-wide CRISPR screening." (PMID 39117798, 2024). "In lymphoma, however, GNAS mutations are rare (0.21% in DLBCL and 0% in follicular lymphoma) with no GNAS activating mutations reported." (PMID 39117798, 2024). "Given that HDAC3 inhibition has been shown to exert anti-lymphoma effects through increasing H3K27ac and promoting apoptosis, we sought to examine whether GNAS KO-induced sensitization is associated with those biological events." (PMID 39117798, 2024). "Moreover, we observe in human lymphoma patients that low GNAS expression is associated with high baseline TE expression and upregulated IFN signaling and shares common disrupted biological activities with GNAS KO in histone modification, mRNA processing, and transcriptional regulation." (PMID 39117798, 2024). "We suggest low GNAS expression as a potential biomarker that reflects viral mimicry priming for enhanced response to HDAC3 inhibition in the clinical treatment of lymphoma, especially the CREBBP wild-type cases." (PMID 39117798, 2024). "Here, using unbiased genome-wide CRISPR screening, we identify GNAS knockout (KO) as a sensitizer of resistant lymphoma cells to HDAC3 inhibition." (PMID 39117798, 2024). "In this study, we report GNAS KO as a molecular sensitizer to HDAC3 inhibition in resistant lymphoma cells." (PMID 39117798, 2024). "GNAS somatic mutations have been recurrently found in hematological disorders such as MDS and lymphoma." (PMID 36035165, 2022). "Specifically, cAMP signaling has been reported to exert anti-lymphoma effects and, to the best of our knowledge, GNAS mutations are not recurrent in DLBCL and follicular lymphoma." (PMID 39117798, 2024). "Our TE transcriptome analysis and immunofluorescence results indicate that GNAS KO may play a role in priming resistant lymphoma to viral mimicry induction upon HDAC3 inhibition." (PMID 39117798, 2024). "Taken together, we identified and validated GNAS KO as a sensitizer to HDAC3 inhibition based on results of distinct sgRNAs and multiple HDAC3-targeting compounds in both human and mouse lymphoma cell lines, showing a consistent and conserved phenotype." (PMID 39117798, 2024).
melanoma (2 papers, 2020 to 2023). A malignant, usually aggressive tumor composed of atypical, neoplastic melanocytes. "Extending from findings in melanoma, we demonstrate that oncogenic mutations that constitutively activate GNAS repress CXCL9/10/11 expression to dampen antitumor T cell response across human cancer types, including ICB-refractory pancreatic and liver cancers." (PMID 37714844, 2023). "Although MC1R activation is a melanoma-specific mechanism of immune evasion, hotspot mutations constitutively activating GNAS are found in diverse cancer types." (PMID 37714844, 2023). "Whereas MC1R activation is restricted to melanoma, GNAS activation by hotspot mutations is observed across diverse cancer types and is associated with reduced CXCL9/10/11 expression." (PMID 37714844, 2023). "Our study implicates MC1R as a melanoma immunotherapy target and suggests GNAS-PKA signaling as a pan-cancer oncogenic pathway inhibiting antitumor T cell response." (PMID 37714844, 2023). "The observed correlation between GNAS mutations with reduced CXCL9/10/11 expression in human cancers prompted us to examine the effect of GNAS R201C in mouse models of tumor types other than melanoma." (PMID 37714844, 2023). "Taken together, these results reveal that GNAS activation represses Cxcl9/10/11 transcription to impair T cell infiltration and effector functions, thus enabling B16 F10 melanoma to escape immunosurveillance." (PMID 37714844, 2023). "Thus, GNAS activation was sufficient to restore immune evasion of MC1R-depleted B16F10 melanoma." (PMID 37714844, 2023).
meningioma (2 papers, 2021 to 2024). A generally slow growing tumor attached to the dura mater. "FD is caused by a mosaic activating pathogenic variant in GNAS gene, and the development of sporadic meningiomas also has genetic predisposition including NF2, TRAF7, KLF4, AKT1 and TERT." (PMID 38287340, 2024). "In this study, we reported a novel GNAS mutation and 1p/22q co-deletion responding to sunitinib in a patient with multiple recurrent meningiomas." (PMID 34722286, 2021). "Here, we shared a novel GNAS mutation and 1p/22q deletion responding to sunitinib in a patient with multiple recurrent meningiomas." (PMID 34722286, 2021). "In our study, this inactivating GNAS mutation was first found in meningioma." (PMID 34722286, 2021). "It remains highly concerned whether GNAS gene is the common genetic predisposition between CFD and meningiomas." (PMID 38287340, 2024). "GNAS mutations and 1p/22q co-deletion were both identified, and amplification at 17q and chromosome 19 was also found in the second recurrent sample, based on which WHO grade II/III meningioma was diagnosed." (PMID 34722286, 2021). "None of them explored GNAS variant and Gαs expression in meningioma specimens and no hypothesis was put forward to explain the co-occurrence." (PMID 38287340, 2024). "Although without GNAS mutation, the meningioma revealed grade 1 Gαs expression." (PMID 38287340, 2024).
metastatic colorectal cancer (2 papers, 2016 to 2021). "Finally, we sought to investigate the role of GNAS mutations in patients with metastatic colorectal cancer." (PMID 27154293, 2016).
migraine (2 papers, 2024 to 2025). "OPRM1 emerges as a pivotal hub, instigating the activation of GNAS and GNB1, subsequently influencing proteins such as RAMP1, RAMP2, RAMP3, CALCB, CALCR, and SLC5A2 all implicated in migraine attacks." (PMID 39215033, 2024). "The network analysis suggested that the specific proteins such as OPRM1, GNB1, and GNAS are interlinked and interacted with the migraine with aura pathological targets like RAMP154, RAMP255, RAMP356, CALCR57, CALCB58, ADM59, IAPP60, and SLC5A261." (PMID 39215033, 2024). "Genes identified within these pathways, including GABRA, GNAS, ADORA, and others, are known to modulate neurotransmitter release, vascular tone, and neuronal excitability, all critical factors in migraine development and propagation." (PMID 39215033, 2024).
mood disorder (2 papers, 2017 to 2019). A cognitive disorder a disturbance in which the person's mood is hypothesized to be the main underlying feature. "It is therefore possible that an interaction of BDNF, CREB1, GNAS, and POMC genes with exposure to chronic stress or traumatic life events increase the risk of cardiometabolic and mood disorders either simultaneously, or through mediating factors." (PMID 28117839, 2017).
myeloid malignancies (2 papers, 2016 to 2024). "Implication of GNAS mutations in MDS or related myeloid neoplasms has not been further investigated." (PMID 27486981, 2016).
myocardial infarction (2 papers, 2013 to 2022). Gross necrosis of the myocardium, as a result of interruption of the blood supply to the area, as in coronary thrombosis. "We found GAPDH, GNAS, and ACTB to be the best combination of reference genes for platelet transcript level studies in healthy individuals, while HDGF, GNAS, and ACTB are the best for studies in patients with the history of myocardial infarction." (PMID 23389042, 2013). "GAPDH, GNAS, and ACTB were shown to be the most stable genes in platelets of healthy individuals, while HDGF, GNAS, and ACTB were the most stable in platelets of patients with the history of myocardial infarction." (PMID 23389042, 2013). "Our results indicate that GAPDH, GNAS, and ACTB are the most stable genes expressed in platelets of healthy individuals and HDGF, GNAS, and ACTB were identified as the most stable reference genes expressed in platelets from patients with the history of myocardial infarction." (PMID 23389042, 2013).
Nephropathy (2 papers, 2021 to 2022). A nonspecific term referring to disease or damage of the kidneys. "Multivariate Cox regression confirmed the results of the univariate analysis in terms of the protective effect of the GNAS CC genotype against the development of BKV-associated nephropathy (relative risk, 0.27; p = 0.036)." (PMID 36297195, 2022). "Along with tacrolimus and MMF-based immunosuppression and rejection episodes, we identified that the common GNAS c.393C>T polymorphism is a prognostic factor for the development of BK viremia and BKV-associated nephropathy." (PMID 36297195, 2022). "The GNAS 393 CC genotype seems to protect renal allograft recipients against the development of BK viremia and BKV-associated nephropathy." (PMID 36297195, 2022). "In conclusion, our study, which involved a large cohort of renal allograft recipients, found that the CC genotype of the GNAS c.393C>T polymorphism is an independent protective factor against the development of BK viremia and subsequent BKV-associated nephropathy." (PMID 36297195, 2022). "We can only speculate about the mechanism underlying the relationship between the CC genotype of GNAS and the reduced risk of BK viremia and BKV-associated nephropathy among renal transplant patients." (PMID 36297195, 2022). "We found, for the first time, that the CC genotype of GNAS, which was detected in 27% of the renal allograft recipients in our cohort, was related to the decreased occurrence of BK viremia and subsequent BKV-associated nephropathy." (PMID 36297195, 2022). "The low number of recipients with BKV-associated nephropathy did not allow us to perform additional multivariate analyses to answer the question of whether the GNAS genotype may be a relevant risk factor promoting progression from BK viremia to BKV-associated nephropathy." (PMID 36297195, 2022).
non-small cell lung carcinoma (2 papers, 2014 to 2022). A group of at least three distinct histological types of lung cancer, including non-small cell squamous cell carcinoma, adenocarcinoma, and large cell carcinoma. "In non-small cell lung cancer, GNAS promotes migration and invasion of cancer cells by altering macrophage polarization." (PMID 35288483, 2022).